PLEKHG1 (pleckstrin homology and RhoGEF domain containing G1)
Description:
Acts as a guanine nucleotide exchange factor (GEF) for RAC1 and CDC42.
Synonyms: KIAA1209; ARHGEF41
Tractability: PROTAC: its protein half-life has been measured.
Gene: Protein-coding gene on chromosome 6 (150,599,848 to 150,843,665, forward strand). Ensembl gene ENSG00000120278.
Subcellular location (Human Protein Atlas): Nucleoplasm
Pathways (Reactome):
Signal Transduction: CDC42 GTPase cycle; RAC1 GTPase cycle
Gene Ontology:
Molecular function: guanyl-nucleotide exchange factor activity; small GTPase binding
Biological process: regulation of small GTPase mediated signal transduction
Cellular component: nucleoplasm; cytosol
Genetic constraint (gnomAD): Loss-of-function variants: 33 observed, 74.79 expected, observed/expected ratio (o/e) 0.44, 90% interval 0.33 to 0.59. The upper end of that interval is the gene's LOEUF score, 0.59, which puts it in group 2 of 6, group 1 being the genes least tolerant of losing a copy. Missense variants: 1,405 observed, 1,625.2 expected, observed/expected ratio (o/e) 0.86, 90% interval 0.83 to 0.9. Synonymous variants: 587 observed, 639.58 expected, observed/expected ratio (o/e) 0.92, 90% interval 0.86 to 0.98.
Homologues: Orthologues: chimpanzee PLEKHG1 (99% identical), macaque PLEKHG1 (97% identical), dog PLEKHG1 (85% identical), rabbit PLEKHG1 (84% identical), guinea pig PLEKHG1 (84% identical), pig PLEKHG1 (80% identical), rat Plekhg1 (80% identical), mouse Plekhg1 (78% identical), tropical clawed frog plekhg1 (58% identical). Paralogues in human: PLEKHG2 (23% identical), TRIO (12% identical), MCF2L (12% identical), KALRN (11% identical), ARHGEF7 (11% identical), TIAM1 (10% identical), PLEKHG4 (10% identical), TIAM2 (10% identical), MCF2 (9% identical), ARHGEF6 (9% identical), VAV1 (9% identical), VAV3 (9% identical), and 10 more.
Diseases named in the same sentence as PLEKHG1 in open-access papers:
PLEKHG1 is named in the same sentence as 17 diseases in open-access papers, as found by Europe PMC text mining. Sharing a sentence is not in itself a finding about the gene and the disease. The quoted sentences say what the papers report.
gastric cancer (2 papers, 2019 to 2022). A primary or metastatic malignant neoplasm involving the stomach. "As the only potential booster gene in RELA relapses, PLEKHG1 (pleckstrin homology and RhoGEF domain containing G1) was significantly upregulated in gastric cancer plasma and associated with poor overall survival." (PMID 36335125, 2022). "Association between the expression of circulating COL6A3, SERPINH1 and PLEKHG1 in gastric cancer and clinicopathologic characteristics." (PMID 31249732, 2019).
ischemic stroke (2 papers, 2019 to 2021). A stroke disorder caused by obstruction of blood flow to the brain, due to thrombotic (local blood clot formation) or embolic (due to a blood clot or other material traveling from another site) event. "Genetic variation in PLEKHG1 is associated with WMH, as well as ischemic stroke and in particular small vessel stroke, suggesting it confers risk via small vessel arteriopathy." (PMID 30659137, 2019). "Genetic variation in PLEKHG1 is associated with WMH and ischemic stroke, most strongly with the small vessel subtype, suggesting it acts by promoting small vessel arteriopathy." (PMID 30659137, 2019).
lymph node metastasis (2 papers, 2019 to 2022). "A higher COL6A3 level was also significantly correlated with lymph node metastasis and poor prognosis in GC patients, while high levels of SERPINH1 and PLEKHG1 mRNA expression were correlated with lower overall survival (OS) in GC patients." (PMID 35892889, 2022).
Alzheimer disease (1 paper, 2019). A progressive, neurodegenerative disease characterized by loss of function and death of nerve cells in several areas of the brain leading to loss of cognitive function such as memory and language. "Finally, in the broader context of traits potentially related to cognition, we find an enrichment of HHMCs in genes associated to “Alzheimer’s disease (cognitive decline)” and “Cognitive decline (age-related)”, with seven associated genes (COX7B2, BCAS3, DMXL1, LIPC, PLEKHG1, TTLL2 and VIT)." (PMID 31186485, 2019).
cerebral palsy (1 paper, 2024). A group of disorders affecting the development of movement and posture, often accompanied by disturbances of sensation, perception, cognition, and behavior. "Despite the potential associations of preterm birth and cotwin fetal abortion with conditions like cerebral palsy and periventricular leukomalacia (PVL), evidence in the literature and the potential involvement of the PLEKHG1 protein pathway with PVL support its role in the patient’s symptoms." (PMID 39202455, 2024).
endothelial dysfunction (1 paper, 2025). In vascular diseases, endothelial dysfunction is a systemic pathological state of the endothelium (the inner lining of blood vessels) and can be broadly defined as an imbalance between vasodilating and vasoconstricting substances produced by (or acting on) the endothelium. "The endothelial dysfunction characteristic of pre-eclampsia may be due in part to dysregulation of the cytoskeleton and intercellular contacts, in which PLEKHG1 is involved." (PMID 41234028, 2025).
glioma (1 paper, 2022). A benign or malignant brain and spinal cord tumor that arises from glial cells (astrocytes, oligodendrocytes, ependymal cells). "Although its biological function is not fully understood, a reverse correlation of PLEKHG1 expression with poor survival in low grade gliomas has been noted." (PMID 36335125, 2022).
ovarian carcinoma (1 paper, 2023). A malignant neoplasm originating from the surface ovarian epithelium. "The differential expression of CCDC170, MTRF1L, ZBTB2, ARMT1, PLEKHG1 and QRSL1 genes affected the overall survival (OS) of ovarian cancer patients." (PMID 37024829, 2023).
preeclampsia (1 paper, 2019). Preeclampsia is a hypertensive disorder of pregnancy that is characterized by new-onset hypertension with proteinuria presenting after 20 weeks of gestation, and depending on mild or severe forms may initially present with severe headache, visual disturbances, and hyperreflexia. "Additional suggestive association with GD was detected for the eSNP of PLEKHG1 (rs7738394 OR = 0.05, P = 0.02), previously linked to the risk of preeclampsia." (PMID 31244887, 2019).
Stroke (1 paper, 2019). Sudden impairment of blood flow to a part of the brain due to occlusion or rupture of an artery to the brain. "We sought replication of the PLEKHG1 SNP in a further 1,202 stroke patients from the MGH WMH study." (PMID 30659137, 2019).
PLEKHG1 also shares sentences with these, for which no sentence is quoted: Cognitive decline (1 paper); infection (1); panic disorder (1); periventricular leukomalacia (1); small vessel stroke (1); vascular dementia (1); white matter hyperintensities (1).